TNF (tumor necrosis factor)
Diseases named in the same sentence as TNF in open-access papers (continued):
Sharing a sentence is not in itself a finding about the gene and the disease.
neurodegenerative disease (continued). "Due to its anti-inflammatory effect, some studies have shown that QUR can be useful as a complementary treatment for neurodegenerative diseases such as AD or PD, by stimulating the expression of HO-1, which reduces NO production and suppress pro-inflammatory markers, TNF-α and IL-1α." (PMID 34220504, 2021). "Our findings demonstrated that BMSCs promote remyelination in the spinal cord of HD-exposed rats via TNFα/RelB-Hes1 pathway, providing novel insights for evaluating and further exploring the therapeutical effect of BMSCs on demyelinating neurodegenerative disease." (PMID 34348774, 2021). "TNFα, oxidative stress, and mTOR (mammalian target of rapamycin) activation are known to induce necroptosis, and the expression or activation of these factors increases with age and neurodegenerative diseases." (PMID 34515928, 2021). "Thus, the uncontrolled release of inflammatory cytokines, such as TNF-α and IL-6, is a key event for neurodegenerative diseases progression." (PMID 33672866, 2021). "After determining the effects of FMU200 on cell viability ROS production and mitochondrial function, we evaluated proinflammatory cytokines, such as IL-6 and TNF-α, which are thought to be involved in mediating neuroinflammation and inducing neuronal death in various neurodegenerative diseases." (PMID 33918172, 2021). "Immunoproteasomes are commonly expressed in cells of the immune system, but they can also be induced in non-immune cells upon exposure to proinflammatory cytokines such as interferons (IFN) or tumor necrosis factor (TNF), environmental stress (e.g., heat shock), aging or neurodegenerative diseases." (PMID 34572540, 2021). "Conversely, inflammation has been increasingly demonstrated to contribute to the development of degenerative changes in the CNS, whereas subsequent increases in the levels of inflammatory cytokines, such as IL-1β and TNF-α, have been proposed to be pathological drivers of neurodegenerative diseases." (PMID 33805302, 2021). "A BBB-penetrating form of etanercept could be an important new drug for the treatment of AD, since tumor necrosis factor (TNF)α plays a role in the chronic neuro-inflammation of AD, as well as other neurodegenerative diseases, such as PD." (PMID 33207605, 2020). "Indeed, increased levels of TNF were identified in patients with autoimmune and degenerative diseases." (PMID 32528961, 2020). "TNF-α inhibitors from natural products might ameliorate neuroinflammation and cognitive dysfunction in neurodegenerative disease patients." (PMID 31991572, 2020). "However, under neuroinflammatory condition, activated microglia play a key role in the pathophysiology of many neurodegenerative diseases by releasing inflammatory and neurotoxic factors such as TNF-α, NO, and reactive oxygen species." (PMID 32316571, 2020). "However, in neurodegenerative diseases, where the chronic neuroinflammation leads to a permanent increase in the concentration of TNF-α, the actions of this protein result in damage to oligodendrocytes, enhanced demyelination, and the disruption of the BBB." (PMID 32752182, 2020). "The pro-inflammatory cytokine TNF-α has been shown to be involved in neurodegenerative diseases." (PMID 32438602, 2020). "Moreover, the increased growth of Streptococcus would raise the levels of IL-6 and TNF-α, and induce neurodegenerative diseases by inducing neuroinflammation." (PMID 31646147, 2019). "Our findings add a new dimension to the pathophysiological role of TNF‐α along with an impaired hypocretin system that may have important implications in health care and neurodegenerative diseases." (PMID 31386303, 2019). "In addition, we evaluated the effects of platycodigenin on the LPS-induced production of TNF-α, IL-6, IL-1β, and IL-10, which are important in neuroinflammation and neurodegenerative diseases." (PMID 31487775, 2019).
neurodegenerative disease (continued). "Therefore, we will review current findings about the role of TNF and IL-1β in animal models of neuroinflammatory conditions and of neurodegenerative diseases, the latter characterized by chronic inflammation." (PMID 29861718, 2018). "TNF-α is a pro-inflammatory cytokine that appears to play a role in neurodegenerative diseases." (PMID 29561785, 2018). "One is to attenuate the inflammatory response through cytokine regulation, and several previous experiments showed that the IL-1β and TNF-α signaling pathways could be inhibited to benefit neurons in neurodegenerative diseases." (PMID 29382106, 2018). "Several studies have shown that aging is accompanied by an increase in the production of pro-inflammatory cytokines, such as IL-6, IL-1β, and TNF-α, which promote chronic inflammation in the elderly and favor the onset and progression of degenerative diseases that are common in this period." (PMID 29232896, 2017). "TNF-α transgenic mice have severe inflammation and exhibit brain and neurodegenerative diseases." (PMID 28923114, 2017). "Awareness of this 1999 report on the rapidity of extracellular cerebral glutamate turnover may now help contribute to the body of accruing evidence that should alter attitudes regarding reports of rapid responses to anti-TNF in neurodegenerative disease." (PMID 27596607, 2016). "Hence modulating the levels of TNF would be worthwhile therapy for various CNS related diseases making TNF as the therapeutic target for neurodegenerative diseases including ALS disease." (PMID 27814735, 2016). "Waning enthusiasm for the amyloid theory now allows many other approaches, including the last 10 years of animal studies, case reports, open trials, and off-label treatments of neurodegenerative diseases, based on neutralizing excessive levels of TNF within the brain, to receive more attention." (PMID 27596607, 2016). "Do these actions of TNF explain the rapid response to etanercept in neurodegenerative disease?" (PMID 27596607, 2016). "Control of glutamate by TNF might also explain why etanercept has often been reported to reverse a number of clinical manifestations of neurodegenerative disease surprisingly rapidly." (PMID 27596607, 2016). "Interleukin-1β (IL-1β), TNF-α and IL-6 are secreted in reactive astrocytes, which may be a first step in the development of several neurodegenerative diseases." (PMID 26729092, 2015). "However, TNF plays a dual role in neurodegenerative disease, since stimulation via its second receptor, TNFR2, is neuroprotective and promotes tissue regeneration." (PMID 25834699, 2015). "In acute or chronic neurodegenerative disease, TNF is released predominantly by activated microglia and may contribute to primary or secondary tissue injury." (PMID 25834699, 2015). "For example, the activation of astrocytes results in the production of diverse pro-inflammatory cytokines, such as IL-1β, TNF-α and IL-6, which may be a first step in the development of several neurodegenerative disease." (PMID 26729092, 2015). "Of relevance for the development of chronic inflammatory and neurodegenerative diseases is the NFκB-mediated induction of inflammatory mediators, in particular cytokines such as IL-6, IL-8, and TNF, and adhesion molecules thus promoting recruitment of immune cells to inflamed tissues." (PMID 25834699, 2015). "Besides NO, excessive production of inflammatory mediators such as proinflammatory cytokines including interleukin-1 beta (IL-1β) and tumor necrosis factor (TNF) from activated microglia contributes to uncontrolled inflammation in neurodegenerative diseases." (PMID 26047814, 2015). "TNF is a key cytokine of the immune system that initiates and promotes inflammation, which under uncontrolled conditions may lead to the development of neurodegenerative diseases." (PMID 25834699, 2015).
neurodegenerative disease (continued). "Nevertheless, the identification of novel agents that can restore the normal function of activated glial cells by means of reducing the production of TNF-α and/or its potentiation of excitotoxicity will be essential in the management of chronic and acute neurodegenerative diseases." (PMID 24966471, 2014). "TNF-α is commonly elevated in the clinic and animal models of neurodegenerative diseases." (PMID 25093162, 2014). "Therefore, overproduction of TNF-α is strongly linked with neuronal damage, and blockage of TNF-α-mediated neurotoxic pathway emerges as an attractive strategy for the treatment of degenerative diseases such as AD and PD." (PMID 25093162, 2014). "While pathological effects of inflammation have been established in other models of neurodegenerative disease, it still remains to be determined whether inflammatory events driven by TNF contribute to degeneration of MSNs during the progression of HD." (PMID 24824433, 2014). "On the other hand, these results could indicate that TNF signaling in the brain has different consequences in the context of mutant htt expression than in other neurodegenerative diseases." (PMID 24824433, 2014). "In many neurodegenerative diseases, persistent injury (such as intraneuronal protein accumulation) promotes the production of proinflammatory molecules, like tumor necrosis factor (TNF)-α, Interleukin (IL)-1β, IL-6, reactive oxygen species (ROS), and nitric oxide (NO)." (PMID 22919540, 2012). "All together these data suggest that selectively targeting the TNF-α pathway using a blood brain barrier-permeable compound could provide an effective therapeutic approach to several human neurodegenerative diseases." (PMID 22277195, 2012). "Tumor necrosis factor (TNF) plays a dual role in neurodegenerative diseases." (PMID 22110694, 2011). "It is well documented that microglia have been recognized as gatekeepers of CNS diseases and immunology and that microglial cells activated by LPS, by hypoxia, or by neurodegenerative diseases produce increased amounts of proinflammatory cytokines such as TNF-α and IL-1β in the CNS." (PMID 21310085, 2011). "As in many other neurodegenerative diseases, TNF and solTNFR1 levels are elevated in cerebrospinal fluid and tissues of PD patients as well as in postmortem PD brains with the highest TNF levels present in areas that have the greatest loss of dopaminergic neurons." (PMID 18925972, 2008). "The major inflammatory cytokines like IL-6, tumor necrosis factor-α (TNF-α), as well as reactive oxygen species are activated by bacterial endotoxin (LPS or lipopolysaccharide), β-amyloid, and interferon (IFN)-γ, which cause neuronal damage and ultimately neurodegenerative disease progression." (PMID 35572539, 2022). "This conclusion may be useful for new therapeutic approaches specifically targeting TNF-α to prevent (prophylactic) or to slow (at diagnosis) PD, as well as potentially other neurodegenerative diseases sharing TNF-α as a contributor to neurodegenerative progression." (PMID 36430754, 2022). "Therefore, TNF has become an important target for treating neurodegenerative diseases." (PMID 36428505, 2022). "Microglia are attracted by a breach in the BBB, and its activation cause increased production of pro-inflammatory mediators such as TNF-α and IL-1b, as well as inducible nitric oxide synthase (iNOS) expression level leading to neuroinflammation and progression of neurodegenerative diseases." (PMID 36698776, 2022). "The role of estradiol is not fully understood, but studies have shown that estradiol plays an important role in neurodegenerative diseases in an anti-inflammatory fashion, since estradiol can upregulate the synthesis and secretion of inflammatory factors, e.g., TNFα, CXCL-8, IL-8, and IL-6." (PMID 35370702, 2022).
neurodegenerative disease (continued). "Our results showing that appropriate doses of hNSC-EV treatment can modulate the release of proinflammatory cytokines TNF-α and IL-1β by activated human microglia suggests that such EVs could be used for treating neuroinflammation in neurodegenerative diseases." (PMID 35656007, 2022). "Hence, developing natural phytochemical drugs against TNF-α may be a potential therapeutic intervention in neurodegenerative diseases." (PMID 31991572, 2020). "Ultimately, combination therapies, using sTNF/TNFR1 antagonists together with TNFR2 agonists, may rebalance pathologically deregulated TNF signaling and induce tissue repair and might be a novel superior therapeutic concept to treat a multitude of inflammatory and degenerative diseases." (PMID 32528961, 2020). "As in other neurodegenerative diseases, neuroinflammation was detected in HD patients as well as in HD animal models like the R6/2 mice, in which pro-inflammatory cytokines such as interleukin 6 (IL-6) and tumor necrosis factor alpha (TNFα) were significantly elevated." (PMID 31208073, 2019). "Therefore, future studies are necessary to evaluate whether heightened central TNF-α releases occur in all the three neurodegenerative diseases analyzed in the meta-analysis, and thereby better explain the etiology of AD, PD and ALS." (PMID 30283455, 2018). "The use of anti-TNF agents in neurodegenerative disease has its critics who largely base their concerns on whether the functional complexities of TNF science, such as the p55 and p75 TNF receptors and membrane versus soluble location of TNF, should be more fully elucidated beforehand." (PMID 27596607, 2016). "The activated microglia release various inflammatory mediators, including tumor necrosis factor-alpha (TNF-α), interleukin (IL)1B, IL6, nitric oxide (NO), reactive oxygen species (ROS), and prostaglandin E2 (PGE2) which have been implicated in various neurodegenerative diseases." (PMID 27400875, 2016). "Thus, as will be discussed, control by TNF of both of these functions gives treatments based on reducing excess cerebral levels of this cytokine a solid therapeutic foundation in neurodegenerative disease, in part because of its essential effects in driving excitotoxicity." (PMID 27596607, 2016). "Therefore, IL-33 is a critical regulator of TNF-α-induced functions in RA-SFs, pointing to a central role of this cytokine in the perpetuation of pro-inflammatory and pro-destructive processes in RA and other inflammatory and degenerative diseases." (PMID 22246057, 2012). "Thrombin induces the expression of proinflammatory cytokines such as NO, IL‐1β, IL‐6, and TNF‐α by activating PAR, promoting inflammation, and driving the progression of neurodegenerative diseases." (PMID 37654024, 2023). "After TBI, microglia was quickly activated and released various inflammatory mediators, including TNF-α, IL-1B, IL6, NO and ROS, which have been proved to be related in some neurodegenerative diseases." (PMID 36869312, 2023). "In some neurodegenerative diseases, TGF-β1 stimulates the production of inflammatory cytokines such as IL-1β and TNF-via phosphorylation of Smad proteins, including Smad2 and Smad3, in rat neurons." (PMID 37240885, 2023). "Notably, mouse retina organoids even reproduce a complex pathology phenotype with combined photoreceptor neurodegeneration and glial pathologies upon combined (not single) application of HBEGF and TNF, two factors previously associated with neurodegenerative diseases." (PMID 37213216, 2023). "Complement component 3 (C3) is also induced in neurodegenerative diseases and is upregulated by proinflammatory cytokines such as IL-1β, gamma interferon (IFN-γ), and tumor necrosis factor alpha (TNF-α) (25, –, 28)." (PMID 37191498, 2023).
neurodegenerative disease (continued). "However, dysregulated TNF-α and related signaling cascades have been reported to lead to persistent increases of synaptic dysfunction, glutamatergic neurotoxicity, and chronic neuroinflammation in the brain in several neurodegenerative diseases such as AD, PS, MS, and ALS." (PMID 37049819, 2023). "Even though inhibition of TNF-α is beneficial for the treatment of certain inflammatory diseases, total neutralization of TNF-α largely failed in the treatment of neurodegenerative diseases." (PMID 37391534, 2023). "Altogether, TNF-α presents an essential role in the generation of neuroinflammation and the immune modulation of microglia by acetate may be a component in the generation of future therapies for neurodegenerative diseases, as long as the time for starting the treatment is taken into account." (PMID 35779458, 2022). "However, neurodegenerative diseases like dementia may also benefit from anti-TNF therapy." (PMID 35651608, 2022). "RES plays an important protective role in mitochondrial impairment, chromatin condensation and inflammation, particularly via decreasing cyclooxygenase-2 (COX-2) and tumor necrosis factor- α (TNF-α) levels hence, beneficial in neurodegenerative diseases." (PMID 36188541, 2022). "Given its role in extinguishing TNF pro-inflammatory signaling, TNFR2 is considered to be protective in neurodegenerative diseases." (PMID 33579029, 2021). "Under the stimulation of TNF-α, TNFR1 was a powerful proinflammatory cytokine that participates in the occurrence of various inflammations and degenerative diseases." (PMID 34804194, 2021). "Previous studies have reported that MT2 was capable of inhibiting the activation of pro-inflammatory cytokines, such as IL-12 and TNF-α and that their inhibition by MT2 contributed to recovery from neurodegenerative diseases." (PMID 33849565, 2021). "C3 is inducibly expressed in astrocytes of most neurodegenerative diseases by inflammatory cytokines such as IL-1β, IFN-γ, and TNF-α." (PMID 34530848, 2021). "The inhibition of TNF-α has been proposed as one of the possible routes to attenuate chronic neuroinflammation in the CNS of patients with ALS and other neurodegenerative diseases." (PMID 32752182, 2020). "This review summarizes the role of TNF-α in neuroinflammation and discusses various phytochemicals that inhibit TNF-α and its neuroprotective mechanism against neurodegenerative diseases." (PMID 31991572, 2020). "Therefore, phytochemicals may ameliorate TNF-α-induced neurological impairments through anti-inflammatory effects, and it could be an effective dietary supplement and nutraceuticals against brain aging and neurodegenerative diseases." (PMID 31991572, 2020). "Proinflammatory cytokines such as TNFα, IL1β, IL-6, and COX2 play an important role in the pathological process of neurodegenerative diseases." (PMID 32560481, 2020). "In contrast to global TNF blockers that neutralize sTNF and tmTNF, this class of therapeutics may induce less severe side-effects and may be therapeutic for other diseases such as MS or neurodegenerative diseases, where complete TNF inhibition is contraindicative." (PMID 32528961, 2020). "Inflammation activated microglia and astrocytes produce tumor necrosis factor-alpha (TNF-α) and nitric oxide (NO) to exacerbate neuronal damage in several neurodegenerative diseases." (PMID 33059746, 2020). "The expression levels of IL-1β, TNFα, COX2, and iNOS are detrimentally related to the progression of neurodegenerative diseases." (PMID 31883536, 2019). "Because activated microglia can produce known neurotoxic substances, such as tumor necrosis factor alpha (TNF-α), microglial presence has suggested that immune-mediated neurodegeneration may contribute to disease origin and/or progression in human neurodegenerative diseases (NDD) (op cit above)." (PMID 30983949, 2019).